ASS1 (argininosuccinate synthase 1)
Diseases named in the same sentence as ASS1 in open-access papers (continued):
Sharing a sentence is not in itself a finding about the gene and the disease.
ovarian carcinoma (15 papers, 2013 to 2025). A malignant neoplasm originating from the surface ovarian epithelium. "In ovarian cancer patients at diagnosis, ASS1 methylation was associated with significantly reduced overall survival and relapse-free survival." (PMID 35582723, 2019). "In ovarian cancer, the loss of ASS1 expression specifically confers resistance to platinum-based chemotherapy." (PMID 27683125, 2016). "These authors also showed that epigenetic inactivation of ASS1 is associated with selective resistance to platinum (Pt)-based treatment in cultured cells and in primary ovarian carcinomas." (PMID 27765932, 2016). "Interestingly, it has been shown that the epigenetic inactivation of ASS1 can be associated with selective resistance to platinum-based treatment in primary ovarian cancer-cultured cells." (PMID 34298999, 2021). "Interestingly, the methylation status of ASS1 has been linked to platinum resistance in ovarian cancer." (PMID 25164070, 2014). "Several cancers, including ovarian cancer, exhibit arginine auxotrophy, a feature marked by defective arginine synthesis due to silencing of argininosuccinate synthetase 1 (ASS1) or arininosuccinate lyase (ASL)." (PMID 38247807, 2024). "ASS1 is elevated in lung, colon, gastric and ovarian cancers, and supports cell proliferation and metastasis." (PMID 35655758, 2022). "Aberrant methylation of the ASS1 promoter correlated with transcriptional silencing in ovarian cancer cell lines leading to selective resistance to platinum-based drugs and conferred arginine auxotrophy and sensitivity to arginine deprivation." (PMID 35582723, 2019). "A significant function for ASS1 in regulating platinum sensitivity via methylation of the ASS1 promoter has been observed in ovarian cancer utilizing the A2780 and A2780CR cell lines." (PMID 25164070, 2014). "Conversely, other tumor types such as colorectal, gastric and ovarian cancer tend to have higher expression of ASS1." (PMID 25164070, 2014). "Epigenetic silencing via methylation of the ASS1 promoter has been previously demonstrated in other cancer types, and a reciprocal relationship between ASS1 expression and cisplatin resistance has also been observed in ovarian cancer." (PMID 25164070, 2014). "A reciprocal relationship between ASS1 expression and platinum resistance has been previously observed in ovarian cancer." (PMID 25164070, 2014). "Underlining this and in contrast with the general definition of ASS1 as a tumor suppressor gene, according to some studies, the overexpression of ASS1 could lead to significantly more migration and proliferation in ovarian cancer cells in vitro." (PMID 41300990, 2025). "However, increased ASS1 levels have also been noted in some types of malignancy such as gastric, colorectal, and ovarian cancers." (PMID 36998052, 2023). "Furthermore, patients treated with first-line platinum/paclitaxel for ovarian cancer had a poor overall and disease-free survival in tumors exhibiting methylated ASS1 compared with unmethylated ASS1." (PMID 34298999, 2021). "In patients who relapsed, ASS1 methylation was significantly more frequent compared to patients who did not relapse, suggesting that hypermethylated ASS1 contributes to treatment failure in ovarian cancer." (PMID 35582723, 2019). "In addition, methylation of the ASS1 promoter does associate with sensitivity to ADI-PEG 20, and in HCC, also corresponds with cisplatin resistance, as previously demonstrated in ovarian cancer." (PMID 25164070, 2014). "Furthermore, it was found that patients treated with first line platinum/paclitaxel for ovarian cancer had a poor overall and disease-free survival if the tumor exhibited methylated ASS1 compared to unmethylated ASS1." (PMID 25164070, 2014). "In addition, an important role for ASS1 in regulating platinum sensitivity via DNA methylation-dependent epigenetic regulation of the ASS1 promoter has been observed in ovarian cancer." (PMID 25164070, 2014).
ovarian carcinoma (continued). "Argininosuccinate synthase 1 (ASS1), an arginine-metabolizing enzyme, is overexpressed in several tumor types, such as lung, colon, gastric, and ovarian cancers." (PMID 37762133, 2023). "Hypermethylation of genes like ASS1, MLH1, and MSX1, and WNT pathway-related genes including DVL1, NFATC3, and SFRP5 was related to poor outcome of ovarian cancer patients treated with platinum-based chemotherapy." (PMID 28641578, 2017). "Thus, this reciprocal relationship between ASS1 expression and cisplatin may be exclusive to HCC and ovarian cancer." (PMID 25164070, 2014).
glioblastoma (14 papers, 2013 to 2025). The most malignant astrocytic tumor (WHO grade IV). "A few groups have highlighted the potential for arginine deprivation treatments targeting arginine-auxotrophic glioblastomas, which are ASS1-deficient and, therefore, unable to synthesise arginine intracellularly." (PMID 39595047, 2024). "Authors have examined the effects of combined treatment with arginine deprivation therapy and cyclin-dependent kinase (CDK) inhibitors in ASS1-deficient glioblastoma cells due to the CDK activity in a variety of cancers." (PMID 39595047, 2024). "ASS1 is the rate-limiting enzyme in arginine biosynthesis, and interestingly, two studies demonstrated that loss of ASS1 sensitizes lymphoma and glioblastoma cells to apoptosis induced by arginine deprivation." (PMID 24745479, 2014). "Epigenetic silencing via methylation of the CpG islands within the ASS1 promoter accounts for loss of ASS1 expression in many solid tumors studied to date, including ovarian, malignant pleural mesothelioma, glioblastoma, myxofibrosarcoma and bladder, as well as in some lymphoid malignancies." (PMID 25164070, 2014). "In 2019, a phase I study on ASS1-deficient recurrent and highly pretreated high-grade glioblastoma multiforme (GBM) patients confirmed safety and induction of stable disease in 80% of patients receiving a PEG-ADI." (PMID 35717443, 2022). "Choy17 reported that a low expression of ASS1 in glioblastoma had the potential to be a predictive marker for therapeutic efficacy." (PMID 31000693, 2019). "Deprivation of arginine is cytotoxic to glioblastoma cells which lack ASS1." (PMID 37214463, 2023). "Moreover, we indicated that loss of ASS1 expression has obvious prognostic value for poor prognosis in BC, which is consistent with other studies in HCC, glioblastoma, and several other cancers." (PMID 35674458, 2022). "Univariate analyses also demonstrated that SLC7A7 and ASS1 were hazardous prognostic factors for glioblastoma, while DDAH1 and NOS1 were proved as protective factors for glioblastoma." (PMID 37214463, 2023). "In ASS1-negative glioblastoma cells, levels of alanine and glutamate are reduced, whereas levels of α-ketoglutarate and pyruvate are increased, indicating that ASS1-negative glioblastoma cells are converting less pyruvate to alanine." (PMID 35910381, 2022). "Interestingly, epigenetic mechanisms have also been shown to play a crucial role in the arginosuccinate synthetase 1 (ASS1)-negative glioblastoma (GBM) tumor model." (PMID 41369374, 2025). "Glioblastomas, which are non-arginine-auxotrophic and proficient in ASS1 production, may also be affected by ADI-PEG20, particularly in combination with ionising radiation." (PMID 39595047, 2024). "While the impact of ADI on glioblastoma (GBM) cells does not appear to be compromised by tumor stem cells leading to drug resistance, other tumor types have exhibited resistance phenomena and withdrawal reflexes due to the re-expression of AS or ASS1." (PMID 39239650, 2024).
Hyperammonemia (12 papers, 2017 to 2025). An increased concentration of ammonia in the blood. "Biochemical indicators such as hyperammonemia, elevated plasma citrulline, low plasma arginine, and increased urinary orotic acid strongly suggest ASS1 deficiency." (PMID 39649700, 2024). "A deficiency in ASS1 disrupts the urea cycle, leading to hyperammonemia and elevated citrulline levels in the blood, urine, and cerebrospinal fluid." (PMID 39649700, 2024). "Ass1 inactivation in mice leads to neonatal lethality, whereas mice with the hypomorphic mutation T389I (Ass1fold mice) show high citrulline blood levels, hyperammonemia, impaired growth and short lifespan." (PMID 36499263, 2022). "ASS1 and argininosuccinate lyase (ASL) are both urea cycle enzymes and deficiency in ASS1 and ASL are genetic disorders that can lead to hyperammonemia in humans." (PMID 38233193, 2024). "Since decreased ASS1 activity results in hyperammonemia and hypercitrullinemia, we first studied whether NH4+max and peak plasma L‐citrulline concentrations during the first metabolic decompensation are associated with residual enzymatic ASS1 activity." (PMID 31469252, 2019).
myxofibrosarcoma (12 papers, 2014 to 2025). A malignant fibroblastic neoplasm arising from the soft tissue. "For instance, ASS1 promoter is frequently hypermethylated in myxofibrosarcoma, resulting in the aberrant loss of ASS1 expression to mediate tumor aggressiveness." (PMID 35910381, 2022). "A previous study demonstrated that in ASS1-deficient myxofibrosarcoma, ASS1 re-expression inhibited tumor growth by inhibiting tumor angiogenesis and inducing G1 phase arrest, indicating that ASS1 was a new tumor suppressor." (PMID 33511116, 2020). "ASS1 deficiency due to promoter methylation is associated with poor outcomes of patients with myxofibrosarcoma and ADI-PEG20 has been suggested as a possible therapeutic target." (PMID 27683125, 2016). "Recently, we reported that aberrant loss of argininosuccinate synthetase (ASS1) caused by promoter methylation may contribute to the enhanced angiogenesis in myxofibrosarcomas." (PMID 25426549, 2014). "Recently, we reported that the antiangiogenic function of ASS1, a rate-limiting enzyme converting citrulline into arginine in the urea cycle, was also attributable to the inhibition of ASS1 on MMP-9 expression in myxofibrosarcomas." (PMID 25426549, 2014). "Analogously, MMP-9 overexpression in the ASS1-deficient and MTAP-deficient myxofibrosarcomas is likely mediated by overexpressed ODC, which converges growth-promoting signals to orchestrate transcriptional regulation." (PMID 25426549, 2014). "Interestingly, besides it role in arginine synthesis, Ass1 gene is recently identified as a novel tumor suppressor gene in myxofibrosarcomas." (PMID 28187218, 2017).
renal cell carcinoma (12 papers, 2013 to 2025). "And in renal cell carcinoma, lncRNA 00312 can also inhibit tumor cell proliferation and invasion in vitro by suppressing miR‐34a‐5p and overexpressing ASS1." (PMID 35674458, 2022). "Downregulation of ASS1 has been reported in melanoma, renal cell carcinoma, mesothelioma, and pancreatic cancer." (PMID 35674458, 2022). "Recent studies have demonstrated that the androgen receptor (AR) could play important roles to promote renal cell carcinoma (RCC) cell proliferation, and other studies have also indicated that suppressing the argininosuccinate synthase 1 (ASS1) could promote proliferation of various tumors." (PMID 31000693, 2019).
glioma (11 papers, 2017 to 2024). A benign or malignant brain and spinal cord tumor that arises from glial cells (astrocytes, oligodendrocytes, ependymal cells). "Ten patients with severe ASS1-deficient recurrent high-grade gliomas were treated with ADI-PEG20 in combination with pemetrexed and cisplatin." (PMID 35898872, 2022). "More recently, we demonstrated that ADI-PEG20 is well tolerated and has promising clinical potential in combination with chemotherapy in a phase I study of recurrent high-grade gliomas that are arginine auxotrophic and ASS1 deficient." (PMID 35113813, 2022). "Research has indicated that in the treatment of glioma, sensitivity to arginine deprivation can be predicted by the methylation of neoplasia-specific CpG islands in the ASS1 and ASL genes, using ex vivo cultures and cell lines." (PMID 37445845, 2023). "ASS1, a tumor suppressor factor, participates in malignant incidences and disease progression by preventing the growth, migration, and invasion of glioma cells." (PMID 38072944, 2023). "For example, a combination of arginine deprivation therapy with radiotherapy or TMZ has shown a good therapeutic effect on ASS1-positive gliomas." (PMID 35898872, 2022). "Recent studies have shown that epigenetic changes in two genes involved in arginine biosynthesis in gliomas, namely CpG island methylation of ASS1 and ASL, lead to decreased protein expression." (PMID 35898872, 2022). "Therefore, researchers have attempted to combine ADT with other treatment modalities to improve the curative effect of the treatment for ASS1-positive gliomas." (PMID 35898872, 2022). "ASL and ASS1 protein levels were mostly undetected in high grade gliomas, whereas BCAT1 was high." (PMID 28245795, 2017). "ADT, by nutrient starvation or exposure to ADI-PEG20, induces adaptive transcriptional upregulation of ASS1 and ASL in glioma cells in vitro, thereby conferring resistance to ADI-PEG20 treatment." (PMID 35898872, 2022). "For infiltrating immune cells, macrophages can express both ASS1 and ASL to synthesize arginine from citrulline, which may be related to the fact that macrophages can account for 30%-50% of cells in the glioma microenvironment." (PMID 35898872, 2022). "In the case of gliomas, 30% of GBM cell lines lack ASS1 expression." (PMID 35898872, 2022). "Additionally, ADI-PEG 20 was shown to reduce intracranial growth of ASS1-negative glioma, extend mouse survival, and enhance the effects of temozolomide in both ASS1-negative and -positive backgrounds, suggesting its potential as a biomarker for glioma treatment." (PMID 37445845, 2023).
lung cancer (11 papers, 2017 to 2025). A malignant neoplasm involving the lung. "Previous studies have shown that lung cancer with high ASS1 expression is associated with poor survival." (PMID 38053661, 2023). "The association of lung cancer with selected tumor cell-specific genes, except ASS1, has been supported by previous studies." (PMID 36397035, 2022). "The main aim of this study was to determine the recommended dose, safety, and tolerability of ADI-PEG 20, cisplatin, and pemetrexed in patients with ASS1-deficient malignant pleural mesothelioma (MPM) or non–small-cell lung cancer (NSCLC)." (PMID 28388291, 2017). "Mutations in ASS1 were involved in the development of lung cancer, but mutations in this gene may be linked with pathogenesis of EOC." (PMID 30970615, 2019). "In conclusion, the expression of ASS1 in lung cancer and its relationship with prognosis still needs to be further explored." (PMID 38053661, 2023). "An additional explanation regarding the favorable prognostic role of ASS1 expression by lung cancer cells comes from a recent study, suggesting that ASS1 is essential to block cancer cell invasion through STAT3 pathway inhibition." (PMID 34344457, 2021). "Increased arginine biosynthesis due to the upregulation of ASS1 has been reported in ovarian, colorectal, gastric and lung cancers, compared to the corresponding normal tissues." (PMID 33809510, 2021). "For lung cancer, ASS1 is overexpressed in LUAD as compared to corresponding normal tissue." (PMID 38053661, 2023). "The expression of ASS1 can be inhibited by HIF1α in lung cancer cells and by promoter methylation." (PMID 35655758, 2022).
osteosarcoma (10 papers, 2015 to 2025). A usually aggressive malignant bone-forming mesenchymal neoplasm, predominantly affecting adolescents and young adults. "We assessed the expressions of ASS1 and P-glycoprotein (P-gp) in clinical specimens and cell lines of osteosarcoma (KHOS), doxorubicin (Dox)-resistant osteosarcoma (KHOSR2), epithelioid sarcomas (ES-X and VAESBJ) and alveolar soft part sarcoma (ASPS-KY)." (PMID 27683125, 2016). "Interestingly, ASS1 knockdown results in increased mTORC1 activity in osteosarcoma cells, potentially due to increased aspartate levels." (PMID 35898872, 2022).
lymphoma (8 papers, 2014 to 2022). A malignant (clonal) proliferation of B- lymphocytes or T- lymphocytes which involves the lymph nodes, bone marrow and/or extranodal sites. "In other tumor cells as reported in lymphoma, methylation of the promoter region can be one of the mechanisms that silence the expression of ASS1, and demethylating agents such as 5-aza-2′-deoxycytidine can induce the re-expression of ASS1 and confer resistance to ADI-PEG20." (PMID 34299249, 2021).
renal carcinoma (8 papers, 2020 to 2024). A carcinoma arising from the epithelium of the renal parenchyma or the renal pelvis. "Sensitive to the arginine levels in the microenvironment, the selective expression of ASS1 provides metastatic renal cancer cells with the ability to utilize nitrogen from BCAA catabolism to produce arginine." (PMID 38136342, 2023). "Some enzymes in the urea cycle are repressed in primary renal cancer cells, while ASS1 is epigenetically reactivated in metastatic populations." (PMID 38136342, 2023). "Metastatic renal cancer cells reactivate ASS1, an enzyme suppressed in primary ccRCC, in order to maintain the invasive potential of metastatic renal cancer cells in vitro and in vivo and to modulate the sensitivity of metastatic cancer cells to arginine depletion." (PMID 38136342, 2023). "The treatment of 786-O with 5-azacitidine (5AC), a DNA demethylating agent, significantly increased ASS1 expression, supporting the hypothesis that ASS1 is epigenetically suppressed in primary renal cancer cells." (PMID 36539415, 2022). "Given that ASS1 expression confers the cells with the ability to survive in the absence of arginine, we hypothesized that the depletion of arginine might regulate ASS1 expression in the renal cancer cells." (PMID 36539415, 2022). "Importantly, we identify the epigenetic reactivation of argininosuccinate synthase (ASS1), a urea cycle enzyme suppressed in primary ccRCC, as a crucial event for metastatic renal cancer cells to acquire the capability to generate arginine, invade in vitro and metastasize in vivo." (PMID 36539415, 2022). "Together, these data suggested that ASS1 is epigenetically controlled in some but not all metastatic renal cancer cells." (PMID 36539415, 2022). "In renal cancer cell, miR-34a-5p directly binds to the 3′ untranslated region of ASS1 to reduce its protein expression, while ASS1P3 serves as a competing endogenous RNA for miR-34a-5p to modulate ASS1 expression." (PMID 35910381, 2022).
urea cycle disorder (8 papers, 2012 to 2024). A genetic inborn error of metabolism characterized by the deficiency of one of the enzymes necessary for the urea cycle. "Four genes (OTC, ASL, CPS1, and ASS1) were responsible for urea cycle disorders, accounting for 14.6% (13/89)." (PMID 34733806, 2021).